KRAS (KRas proto-oncogene, GTPase)
Diseases named in the same sentence as KRAS in open-access papers (continued):
Sharing a sentence is not in itself a finding about the gene and the disease.
cancer (continued). "The observed downregulation of critical oncogenes such as KRAS, NRAS and MYC further highlights the potential of this combination therapy to target multiple oncogenic pathways, reducing the likelihood of cancer cell survival and proliferation." (PMID 40307570, 2025). "We found that ECGs were significantly enriched in the TNF‐α/NF‐κB, KRAS and IL‐6/JAK/STAT3 pathways across nearly all cancer types." (PMID 40576208, 2025). "In basal cancer cells, enrichment of EMT coincided with increased immune response, KRAS signaling, apoptosis and angiogenesis, and decreased oxidative phosphorylation (OXPHOS), myc targets and E2F targets with age." (PMID 41188599, 2025). "Counteracting immune-evasive mechanisms driven by oncogenic KRAS sensitizes tumors to immunotherapy, supporting the rationale for combination regimens in NSCLC and other RAS-driven cancers." (PMID 41471277, 2025). "As KRAS, NRAS, and HRAS are commonly altered genes in cancer, the pursuit of RAS inhibitors remains an active area of contemporary drug development research." (PMID 39858030, 2025). "LUAD exhibited a particularly high number of 7 mutated genes with significant co-occurrence with CNAs compared to other cancer types – including EGFR, GATA2, GBA, GLI3, KAT6A, KRAS and NOTCH3." (PMID 41415395, 2025). "Rat sarcoma (RAS) proto-oncogenes play an important role in the development of cancer, with the three RAS genes (HRAS, NRAS and KRAS) being the most commonly activated drivers of cancer within this family." (PMID 40868227, 2025). "KRAS protein, once bound to GTP, is capable of interacting with downstream proteins and activates the effector signaling pathways that drives cancer growth." (PMID 40230862, 2025). "So far, several KRAS G12C inhibitors, including AMG510 (Sotorasib), MRTX849, LY3537982, GDC-6036 and D-1553, have gained approval for cancer treatment." (PMID 39820726, 2025). "While KRAS mutational status could not be inferred from these datasets, our analyses support the presence of an epithelial subpopulation in the human pancreas of cancer-free individuals that mirrors the progenitor-like state observed in mice." (PMID 40661354, 2025). "For instance, as mentioned in the introduction, KHSRP interacts with hnRNPA1, a protein known to resolve G4 structures at telomeres and in the promoters of genes such as KRAS and TRA2B, thereby modulating their transcription in cancer cells." (PMID 39763191, 2025). "Given that proto-oncogenes such as MYC, KRAS, RET, and VEGF are often overexpressed in human cancers, we analyzed the regulatory effect of BTO-28 on proto-oncogene transcription in HT-29 cells." (PMID 40966493, 2025). "Contrary to the immune contexture of EGFR and ALK altered tumors, the KRAS driven NSCLC displays predominantly IE and inflamed TME types, which suggests a different route to cancer immune evasion." (PMID 40809430, 2025). "Western blot analysis of sorted iRFP-positive cells confirmed decreased levels of both KRAS and phosphorylated ERK in all cell lines, indicating effective target engagement and suppression of downstream signaling in recipient cancer cells." (PMID 41322195, 2025). "On the other hand, SFKs interact with both KRAS and YAP, modulating their activities and contributing to aggressive cancer phenotypes and drug resistance." (PMID 40895190, 2025).
cancer (continued). "Taken together, these results show that the optimized V2 inverted chimeric siRNA demonstrates marked improvements in targeting both MYC and KRAS, resulting in attenuated MAPK signaling and synergistic inhibition of cancer cell viability." (PMID 40762837, 2025). "For example, the cancer vaccine ELI-002 2P consists of the amphiphile (Amph) modification of G12D- and G12R-mutant KRAS peptides (Amph-Peptide-2P) and a CpG oligonucleotide adjuvant (Amph-CpG-7909), which enhances lymph node delivery and the immune response." (PMID 40361439, 2025). "The inhibition of GDC-0879 on MEK restrains the proliferation of cancer cell lines carrying wild-type BRAF with different KRAS status (81% KRAS mutant, 38% KRAS wild-type)." (PMID 40781221, 2025). "We found 6 significant gene-cancer type pairs impacted by CNAs where samples also contained eccDNA copies of the gene, including PIK3CA in BRCA, KRAS in COAD and LUAD, BRAF in SKCM, and EGFR in LUAD." (PMID 41415395, 2025). "Although numerous studies have suggested that m6A methylation plays crucial roles in the occurrence and development of various cancer types, including NSCLC, the role of m6A methylation in chemoresistance in KRAS-mutant NSCLC remains elusive." (PMID 39960727, 2025). "The PD-L1 expressions of KRAS-mutant cells were substantially removed after antioxidant therapy, and FGFR1 gene downregulation diminished the cancer development and decreased PD-L1 expressions." (PMID 40075634, 2025). "In conclusion, the results from this study support the therapeutic potential of dual inhibition of AXL and SRC towards KRAS mutant NSCLC therapies and will aid in our understanding of molecular mechanisms behind TKI therapies in KRAS mutant harboring cancers." (PMID 39941857, 2025). "For example, KRAS upregulates the expression of immune modulators, such as IL-10, TGF-β, and PD-L1 on cancer cells, leading to inhibition of T cell cytotoxicity." (PMID 40333779, 2025). "Some aggressive cancer subtypes, such as basal‐like PDAC, display reduced dependence on KRAS and heightened reliance on YAP/TAZ activity, often driven by Src family kinase (SFK) signaling." (PMID 40895190, 2025). "Both downstream activation through alternative pathways and upstream activation occurs after inhibition of KRAS G12C, which correlates with the increased expression levels of EGFR, HER2, FGFR, and c-MET observed in cancer cells." (PMID 40597785, 2025). "Thus, DA-Raf may also function as an invasion suppressor protein in the KRAS-mutant cancer cells." (PMID 41120211, 2025). "We conducted NGS using the Ion Torrent platform with a custom panel covering 50 cancer-related genes, including SMARCA4 and KRAS." (PMID 39777351, 2024). "Analysis of the function of SMAD3 using GSEA showed that high SMAD3 expression was related to multiple types of cancer including NSCLC, and cancer-related pathways such as PI3K/Akt/mTOR and KRAS." (PMID 38493128, 2024). "The rat sarcoma (RAS) gene family includes Kirsten RAS (KRAS), Harvey RAS (HRAS), and neuroblastoma RAS (NRAS), which are the most prevalent and foremost genetic alteration in human cancers." (PMID 39749200, 2024). "Targeted approaches in cancer management have been met with great success in various cancer types including BRAF in breast cancer or EGFR and KRAS in lung cancer." (PMID 39360054, 2024). "Nevertheless, considerable progress has recently been made in the development of KRAS and MYC inhibitors for the treatment of cancer starting to show promising clinical results, likely bringing the perception of these oncogenes as “undruggable” to an end." (PMID 39164274, 2024).
cancer (continued). "Small molecule inhibitors of the GDP KRAS-OFF state are emerging, such as sotorasib (LUMAKRAS) and adagrasib (KRAZATI) for KRASG12C mutant cancers, and MRTX1133 for KRASG12D mutant cancers." (PMID 38755258, 2024). "Moreover, we revealed that co-inhibition of SUMOylation and MEK could conquer KRAS-mutant cancers." (PMID 38992694, 2024). "Studies have shown that co-inhibition of SHP2 and MAPK pathway signaling such as EGFR, KRAS, and MEK effectively inhibits cancer cell growth and counters adaptive cancer resistance." (PMID 39014007, 2024). "Further investigations on an expanded array of KRAS- and/or MYC-dependent cancers are warranted to support the use of PPRHs in combination." (PMID 39457457, 2024). "During this metabolic process, oncogenes such as YAP, KRAS, and c-MYC increase the expression of GLUT1 in cancer cells." (PMID 38841361, 2024). "We observed similar results, namely BAY 11-7082 treatment leads to significant increase in PARP-cleavage in NRAS, KRAS, and HRAS mutant-cancer cell lines." (PMID 38982514, 2024). "In human cancer, PAAD patients are among the highest populations affected by KRAS, followed by CRC and LUAD." (PMID 39056802, 2024). "Among these pathways, there were key signaling routes such as KRAS, NOTCH, TGF-β, MYC, and WNT known to play significant roles in cancer progression and therapy resistance." (PMID 39061234, 2024). "Cancer cell lines Hs 578 T (HRAS-G12D) and T24 (HRAS-G12V), as well as the KRAS-G12C mutant MIA PaCa-2, express high levels of Gal1, while HEK cells have, in comparison undetectably low levels of Gal1." (PMID 38982284, 2024). "This sponging leads to the subsequent upregulation of BMI1, KRAS, AKT3, KLF12, and NAMPT, along with several other cancer-promoting genes, thus promoting a more aggressive phenotype." (PMID 39039064, 2024). "Recently, BI-3406, another SOS1 inhibitor was demonstrated to be more potent and selective for inhibiting SOS1, decreasing KRAS-GTP levels and suppressing cancer cell proliferation." (PMID 38978742, 2024). "In this report, we demonstrate that Hh signal contributes to the re-expression of KRAS and reactivation of ERK and, thus, induction of acquired resistance against KRASG12C inhibitor in cancer cells." (PMID 38225225, 2024). "Mutations in the rat sarcoma viral (RAS) oncogene family, specifically KRAS, HRAS, and NRAS, are among the most prevalent among human tumorigenesis found in 30% of all cancer types included." (PMID 39184150, 2024). "MAPK cascade plays a key role in tumorigenesis wherein genetic alterations in KRAS and EGFR genes are leading trigger factors of cancer." (PMID 38374954, 2024). "The development and expansion of cancer stem cells are regulated by several signaling pathways, and in CRC, this process is selectively controlled by RAS isoforms, with the KRAS isoform being the most potent inducer of stemness characteristics." (PMID 39061234, 2024). "KRASG12C mutation (glycine-to-cysteine substitution at codon 12) is one of the most common KRAS mutations, and it may occur in a variety of tumor types, such as non-small-cell lung cancer (NSCLC), colorectal cancers (CRC), pancreatic cancers, and other cancers." (PMID 39010022, 2024).
cancer (continued). "The combination strategies of KRAS G12C inhibitors and YAP/TAZ inhibition exert synergistic effects in multiple KRAS G12C–mutant cancer cell lines that exhibit intrinsic or acquired resistance to KRAS G12C inhibitors." (PMID 39704172, 2024). "By cross-referencing these sources, we identified five top oncogenes—ALK, EGFR, GNAS, KRAS, and PIK3CA —due to their frequent occurrence and their critical roles in multiple cancers." (PMID 39684787, 2024). "Among the top 20 signatures identified from GSEA, several cancer‐related signatures, including the CCA signature and EGFR & KRAS signaling signatures, were significantly enriched in both cohorts." (PMID 38526177, 2024). "These distinct sites reflected the interface between KRAS and CYPA, underscoring that the mechanism of drug action heavily impacts the probable mechanisms of escape selected for by cancer cells." (PMID 38668053, 2024). "Challenges in targeting KRAS through direct targeting of the GTP binding pocket include the high affinity for its native substrate GTP, which is abundant in cancer cells." (PMID 38473386, 2024). "Next, we continued our selectivity assessmentby testing the antiproliferative activity of the top three compoundsfrom each round on KRAS, HRAS, or BRAF mutant cancer cells." (PMID 38758695, 2024). "Two classical examples are the synergistic interaction between activating mutations in MYC and amplification of RAS and the mutually exclusive relationship between alterations in KRAS and BRAF across many cancer types." (PMID 38687804, 2024). "BAY 11-7082, an inhibitor of IκBα kinase, attenuates the growth of NRAS, KRAS, and HRAS mutant cancer cells in cell culture and in mouse model." (PMID 38982514, 2024). "The simultaneous targeting of KRAS-MEK and mTORC1/2 prevents the upregulation of ERK and AKT phosphorylation, leading to the inhibition of protein translation and cancer cell survival pathways." (PMID 38473413, 2024). "Accordingly, substantial efforts have been devoted to targeting the receptor tyrosine kinase (RTK)/RAS/MAPK pathway, yielding numerous small-molecule inhibitors of pathway components RTKs, KRAS, RAF, MEK1/2, and ERK1/2 that show efficacy in cancer patients." (PMID 38842946, 2024). "We next measured the apoptosis induction using annexin V and PI staining method and found a significant increase in apoptosis induction in NRAS, KRAS, and HRAS mutant-cancer cell lines upon treatment with BAY 11-7082 as compared to DMSO treated cells." (PMID 38982514, 2024). "Taken together, our data suggest that an Hh signal is required for the re-expression of KRAS, reactivation of ERK, and sonidegib blocks the generation of acquired resistance in cancer cells after treatment with a KRASG12C inhibitor." (PMID 38225225, 2024). "Current studies propose that MYC plays a crucial role in KRAS-driven cancers, although the connection between MYC and drug resistance in these types of cancers remains an unanswered question." (PMID 39457457, 2024). "The RAS genes (KRAS, NRAS, HRAS) hold significant historical importance as they were the first human oncogenes discovered in the field of cancer research." (PMID 39455841, 2024). "Oncogenic KRAS promotes the upregulation of the glucose transporter GLUT1, which enhances the uptake of glucose by cancer cells, in addition to other glycolytic enzymes such as HK1, HK2, and LDHA." (PMID 38668053, 2024).
cancer (continued). "Specifically, 76.9% (10 out of 13) of cancer signalling hallmarks exhibited back‐splicing activity in at least half of the GBC samples, such as ‘KRAS signalling’ and ‘Hedgehog signalling’." (PMID 39428382, 2024). "The RAS family proto-oncogenes (KRAS, NRAS, HRAS) play a crucial role in cellular signaling and cancer biology." (PMID 39001451, 2024). "The aim of our study was to elucidate the relationships between KRAS and its post-translational modification, MEK-inhibitor, and cancer cell response to chemotherapy with cisplatin in vitro." (PMID 38225605, 2024). "In samples from more than 20 cancer types, the genes regulated by eRNAs were found to be involved in canonical cancer pathways, including MYC, KRAS proto-oncogene (KRAS), and DNA repair pathways." (PMID 38863031, 2024). "In order to enhance the efficacy of the KRAS vaccine and anti-PD-1 treatment, an anti-CD38 antibody (daratumumab) is being administered with the objective of facilitating the killing of cancer cells by the immune system." (PMID 39329742, 2024). "For example, long-term treatment with PI3K inhibitors in KRAS-mutant cancer cells can lead to the re-activation of AKT, a process dependent on KRAS’s downstream effector, ERK2." (PMID 39614261, 2024). "It will provide a versatile solution to the genetic heterogeneity observed in different cancers harboring HRAS, NRAS, and KRAS, making it a valuable tool to treat various malignancies with RAS mutations." (PMID 38982514, 2024). "These DNA targets consisted of multiple KRAS, BRAF and NRAS SNPs, which are commonly used as cancer markers for the detection and characterization of various cancer types, for example, in liquid biopsies." (PMID 39201654, 2024). "We treated multiple NRAS (SKMEL-103, M245, and SKMEL-2), KRAS (AsPC1, PANC1, and SU.86.86), and HRAS (RH-36 and SMS-CTR) mutant cancer cell lines with different concentrations of BAY 11-7082 and measured cell viability." (PMID 38982514, 2024). "In this present work, we studied the response to individual and combinatorial MYC and KRAS targeting PPRHs in KRAS and MYC-deregulated, dependent, and sensitive prostate PC-3 and pancreatic AsPc-1 cancer cells." (PMID 39457457, 2024). "In cancer cells, The NFE2L2 expression is regulated not only vai Keap1-mediated degradation of protein, but also via oncogenic signaling pathways like KRAS-BRAF-MYC." (PMID 39877159, 2024). "CHK1i is toxic to a variety of cancer and normal cells, making it poorly targetable to RAS or KRAS mutants." (PMID 39682179, 2024). "Our study identifies BAY 11-7082 to be an efficacious inhibitor for treating RAS oncogene (HRAS, KRAS, and NRAS) mutant cancer cells." (PMID 38982514, 2024). "Several recent studies also have shown that GLI can be activated by oncogenic pathways such as KRAS and TGF-β, independently of the Hh ligand-PTCH1-Smo route in cancer cells." (PMID 38225225, 2024). "However, targeting SMARCA4, regardless of KRAS mutation, may prove a successful method of treating cancers." (PMID 38446332, 2024). "This study shows that monoubiquitination of KRAS and NRAS at lysine 128 (K128) enhances RAS binding to GTPase-activating proteins to restrict RAS activity, a mechanism that is dysregulated in cancer tissues." (PMID 38858602, 2024). "Kirsten rat sarcoma viral oncogene (KRAS) plays a pivotal role in cancer-macrophage communication, with KRASG12D protein being released from autophagy-dependent ferroptotic cancer cells through an oxidative stress response." (PMID 38594265, 2024). "Through structure-based design, the authors identify the KRAS-G12V specific affinity-enhanced TCR, offering great promise for advancing cancer immunotherapy." (PMID 38684865, 2024).